SPINK14 (serine peptidase inhibitor Kazal type 14 (putative))
Description:
May be a serine protease inhibitor.
Synonyms: SPINK5L2
Tractability: Antibody: UniProt places it where antibodies can reach, with high confidence; UniProt predicts a signal peptide or a membrane-spanning region; its Gene Ontology location is reachable by antibodies, with medium confidence.
Gene: Protein-coding gene on chromosome 5 (148,168,546 to 148,175,619, forward strand). Ensembl gene ENSG00000196800.
Subcellular location: Secreted
Gene Ontology:
Molecular function: serine-type endopeptidase inhibitor activity
Biological process: negative regulation of proteolysis
Cellular component: extracellular region
Genetic constraint (gnomAD): Loss-of-function variants: 2 observed, 5.62 expected, observed/expected ratio (o/e) 0.36, 90% interval 0.14 to 1.12. That is too few expected variants to judge how well the gene tolerates losing a copy. Missense variants: 45 observed, 42.87 expected, observed/expected ratio (o/e) 1.05, 90% interval 0.83 to 1.35. Synonymous variants: 19 observed, 14.67 expected, observed/expected ratio (o/e) 1.29, 90% interval 0.9 to 1.82.
Homologues: Orthologues: chimpanzee SPINK14 (99% identical), macaque SPINK14 (92% identical), dog SPINK14 (74% identical), rabbit SPINK14 (72% identical), guinea pig SPINK14 (67% identical), rat Spink14 (66% identical), mouse Spink14 (65% identical), pig SPINK14 (65% identical). Paralogues in human: SPINK7 (33% identical), SPINK13 (30% identical), SPINK9 (27% identical), SPINK2 (26% identical), SPINK8 (23% identical).
Diseases named in the same sentence as SPINK14 in open-access papers:
SPINK14 is named in the same sentence as 1 disease in open-access papers, as found by Europe PMC text mining. Sharing a sentence is not in itself a finding about the gene and the disease.
SPINK14 shares sentences with these, for which no sentence is quoted: tumor (1 paper).